CD4 (CD4 molecule)
Diseases named in the same sentence as CD4 in open-access papers (continued):
Sharing a sentence is not in itself a finding about the gene and the disease.
tumor (continued). "Tumor outgrowth is controlled by CD4 and CD8 T cells, there are three phases of tumor-immunity, namely elimination, equilibrium and escape." (PMID 38082437, 2023). "Existing evidence indicates that activated microglia in the tumor microenvironment can inhibit the activity, function, and quantity of tumor-infiltrating lymphocytes (TILs, like CD4+ or CD8+ T cells) with anti-tumor effects." (PMID 37700840, 2023). "The tumor-infiltrating lymphocytes in CRCs consist of anti-tumorigenic CD4+ T cells, such as Th1 or Th22 cells, and pro-tumorigenic CD4+ T cells, such as Th17 or immunosuppressive Tregs." (PMID 37511431, 2023). "Anti-TREML4 mAb-antigen conjugates can generate antigen-specific CD8+ and CD4+ T cell immunity to tumor and viral antigens, or antigen-specific tolerance, when targeted in the presence or absence of external adjuvant." (PMID 37662903, 2023). "Dendritic cells play a pivotal role in tumor control via the uptake and presentation of tumor antigens, followed by their migration to lymph nodes, and the DC-dependent activation of naïve tumor antigen-specific CD4 or CD8 T-cells." (PMID 37190135, 2023). "These antigen-specific CD4+ T cells are reported to enhance the efficacy of anti-tumor CD8+ T cell responses, and mediate long-lived protection against subsequent tumor recurrence." (PMID 37051250, 2023). "An adaptive immune response to cancer is made possible by the subsequent robust response of T cells (CD8 + and CD4 + T lymphocytes) to tumor antigens." (PMID 37259066, 2023). "There was a significant increase in the number of CD4+ T cells and Tregs in the IL-6-depleted tumors indicating that the tumor cell derived increase in IL-6 secretion following Kindlin-1 loss can drive changes in Tregs in vivo." (PMID 36883731, 2023). "For instance, they boosted the production of Th1 cytokines (IL-2, IFN-γ, and TNF-α), which helped to kill tumor cells through increased production of CD4+/CD8+ lymphocytes." (PMID 37047572, 2023). "Single-cell RNA sequencing revealed that Mito-ATO inhibits the expression of genes for OXPHOS and glycolysis in G-MDSCs and Tregs and facilitates the infiltration of CD4+ T cells in the tumor microenvironment." (PMID 36831432, 2023). "Studies in bladder cancer cell lines have found that depletion of CD4+ T-cells in the TME increases tumor size and dampens the effect of immune checkpoint inhibition." (PMID 38201559, 2023). "Tumor cells increase their expression of CD39 to suppress both CD4+ and CD8+ T cell proliferation and cytotoxicity in the TME." (PMID 38263981, 2023). "Immunosuppressive FoxP3+ CD4+ regulatory T cells (Tregs) are crucial immune components within the tumor microenvironment (TME), initially contributing to immune homeostasis and self-tolerance." (PMID 37892995, 2023). "In our study, YTHDF1 deficiency significantly promoted tumor MHC-I expression and subsequently led to an enhanced T-cell recognition as evidenced by the increased infiltration of CD4+ and CD8+ T cells, and expanded TCR clone type in the TME." (PMID 36650153, 2023). "Single agent anti-PD-1 or anti-CTLA-4 increased the infiltrating ICOS+ CD4+ T cells to a similar degree, but combination blockade interestingly had a greater effect on the percentage of tumor-infiltrating lymphocytes (TILs) composed of ICOS+ CD4+T cells." (PMID 37449205, 2023). "Given the crucial role of CD4+Treg in tumor progression, it is essential to gain a deeper understanding of the distinct functional subtypes of CD4+Treg." (PMID 38250084, 2023). "Immune score and tumor purity were significantly higher in C1 than in C2, and CD4+ memory activated T cell, Tfh, Tregs, and macrophage M0 were higher infiltrated in HCC and C1 group." (PMID 37881434, 2023). "In metastatic colorectal cancer, this subpopulation has been found to favor immunosuppression and tumor growth while in urological cancer it is correlated with differentiation of CD4+ naïve T cells to the pro-tumoral Th2 phenotype." (PMID 37006319, 2023).
tumor (continued). "The examination of PD‐1, a marker of T cell exhaustion, found a decreased expression in CD8+ and CD4+ T cells when tumor cells were transfected with G9a‐shRNA." (PMID 36971192, 2023). "They represent susceptible tumor population killed directly by the effector CD8+ T cells and indirectly by CD4+ T cells through cytokines at a rate of δx and δc, respectively." (PMID 36766849, 2023). "Naïve T cells (CD4+CD25−) were purified from the spleen of tumor bearing mice and labeled with CFSE." (PMID 37122749, 2023). "CD4+ T lymphocytes within the tumor microenvironment (TME) play important roles in tumor immune surveillance." (PMID 36690649, 2023). "This tumor control requires IFNγ production by CD4 T cells, MHC-II expression on tumor cells, and is independent of host immune cells." (PMID 37185301, 2023). "Mice injected with GL261-CIITA express de novo MHC class II molecules and reject or strongly retard tumor growth as a consequence of rapid infiltration with CD4+ and CD8+ T cells." (PMID 36993983, 2023). "CD4+Foxp3+ regulatory T cells (Tregs) are central regulators of anti-tumor immune responses and they represent a major cellular mechanism of tumor immune evasion." (PMID 36865537, 2023). "CD4+ Tregs function as immune suppressor cells that negatively regulate anti-tumor immunity in most cancers." (PMID 37834375, 2023). "Compared with non-NPs administration, nanomaterial encapsulated drugs increased the half-life by 40 times, took advantage of EPR effect to accumulate drug concentration in the tumor, and increased the number of immune cells (CD4+ and CD8+ T cells) by 20 times." (PMID 37600822, 2023). "PD-L1 expression and the recruitment of tumor-infiltrating CD4+ and CD8+ T lymphocytes were further assessed in harvested CT26- and H1975-derived tumors." (PMID 37027467, 2023). "The results of our current research are in line with previous studies showing that the lower the level of CD4+ T lymphocyte infiltration, the worse the prognosis of the patient and the more advanced the stage of the tumor would be." (PMID 37144126, 2023). "FABP5 showed the most significant correlation with tumor-infiltrating immune subsets, such as B-cells, CD4+ T-cells, CD8+ T-cells, neutrophils, macrophages, and dendritic cells." (PMID 36950134, 2023). "Tumor growth was similar in Cd4;Tcf7fl/fl mice treated with anti–PD-L1 antibody compared with Cd4;Tcf7+/+ mice on the same treatment, possibly indicating that other compensatory mechanisms limit antitumor responses in this model." (PMID 36239683, 2023). "We found that inhibition of B7-H3 in mouse models with high mTORC1 activity inhibits tumor growth, associated with increased infiltration of cytotoxic CD38 and CD39-double-positive CD4+ T cells and increased IFN-γ responses and MHC-II expression." (PMID 36869048, 2023). "The number of Tregs increases in the tumors and blood of HCC patients compared to that in healthy controls, and the percentage and absolute number of CD4+ CD25+ T cells are significantly increased in the tumor periphery." (PMID 36769116, 2023). "Next, we analyzed the impacts of simultaneous PD-L1 blockade and CD4+ T cell depletion on the tumor immune microenvironment." (PMID 36969495, 2023). "In this study, depletion of TREG cells led to increased activation of cDC2 which migrated to the tdLN and subsequently improved anti-tumour CD4+ T cell responses." (PMID 37139854, 2023). "A. muciniphila restores the effectiveness of PD‐1 inhibition by boosting CCR9+CXCR3+CD4+ T lymphocyte recruitment to mouse tumor beds." (PMID 37937304, 2023). "We directly challenged NOS2KO animals with tumors to evaluate the effects of their specific deletion of Nos2 in the entire T-cell compartment (encompassing CD8+ and CD4+ T cells) on tumor growth." (PMID 36574610, 2023). "As a fight-back mechanism, tumor cells produceCD4+CD25+FOXP3+ T-regulatory (Treg) cells from CD4+T cells by shedding multitude of chemokines." (PMID 38038865, 2023).
tumor (continued). "Both tumor and healthy CD4+ and CD8+ T cells predominantly displayed an effector memory (TEM) phenotype." (PMID 37484198, 2023). "The concentration of glutamate in the tumor environment decreased, and there was an increase in CD4+ T cells, major players in the adaptive immune response, and a decrease in regulatory immune cells within the tumor." (PMID 37298093, 2023). "CD4 T cells can differentiate into various Th subsets that can induce, modulate and maintain immune responses to tumor antigens." (PMID 37880313, 2023). "This was also observed in the CD4+ T cell compartment, with a decrease in the percentage of tumour-infiltrating CD3+CD4+CD27+ post-FLOT chemotherapy compared with the treatment-naïve tissue (16.22 ± 3.6 vs. 4.64 ± 1.8%, p = 0.03)." (PMID 35986757, 2023). "These immune cells, including CD8+ T cells, CD4+ T cells, macrophages, and dendritic cells, play a crucial role in inhibiting tumor growth." (PMID 37745716, 2023). "Tumor‐infiltrating CD4+ T cells also express CD39, which express higher levels of PD‐1 and produce fewer cytokines." (PMID 37829505, 2023). "Cells stressed by low‐dose irradiation create an highly cytokine driven surrounding swimming with effector CD4 and CD8+ T cells, ICD proteins, neoantigens, various TNF and IL factors mediating which cause secondary cytolytic tumor killing." (PMID 36411943, 2023). "One of the essential immune cells favouring tumor growth and regulating the immunesurveillance is the CD4+CD25+Foxp3+ Treg cell." (PMID 37056346, 2023). "Activated CD4+ T cells possess specific effector functions and play an essential role in tumor immunity." (PMID 38273850, 2023). "Successful depletion of CD4 T cells was confirmed by flow cytometry 7 days following tumor implantation." (PMID 37072485, 2023). "Our results strongly support the clinical development of ACT-based therapeutic strategies that include appropriate activating stimuli for myeloid cells to unleash the full potential of CD4+ T cell effector functions against immune-evasive tumours." (PMID 37316667, 2023). "In HCC, LDHA silencing has been demonstrated to impede tumor development and promote CD4+ T-cell infiltration." (PMID 37287752, 2023). "CD4+ T cells can regulate cytolytic mechanisms or indirectly attack and kill tumor cells through modulation of a number of cytokines, including TME and others." (PMID 36697459, 2023). "And we investigated the relationship between PKM2 expression and tumor-infiltrating immune cells represented by fibroblasts, B cells, T cell CD4+, T cell CD8+, NK cells, and mast cells." (PMID 36865483, 2023). "The anti‐tumour immunity of mRNA‐based cancer vaccines elicits antibody, B cell‐mediated humoral reaction and CD4+/CD8+ T cells response." (PMID 37612832, 2023). "In C34, α-SMA-stained tumor-proximate stromal cells (most likely fibroblasts) were also infiltrated with CD4+ T cells." (PMID 37349501, 2023). "Intriguingly, we noted reduced GPR15 expression on tumor infiltrating CD4+ and CD8+ T cells in GPR15L-treated Gpr15-Het mice compared to the PBS-treated Gpr15-Het mice." (PMID 38074634, 2023). "Targeting CCR4 was shown to be able to improve immunity by preventing Treg (CD4+) entry into the tumor microenvironment, and subsequently overcome sorafenib resistance." (PMID 37152990, 2023). "The number of tumour infiltrating Tregs gradually increases throughout the progression of PDAC and is strongly associated with poor prognosis due to their ability to suppress tumour specific CD4+ and CD8+ T cells and NK cells." (PMID 37190281, 2023). "Tumor masses with volume >120 mm3 were harvested and the presence of T Helper (CD4+) and Cytotoxic T (CD8+) cells in the single tumors was quantified via flow cytometry." (PMID 37503351, 2023). "We found that when co-cultured with CD4+ T cells from tumors in Cd4;Tcf7+/+ mice, 7940b cells expressed more Cd274 compared with tumor cells cultured alone." (PMID 36239683, 2023).
tumor (continued). "The pDCs can process synthetic tumor-derived peptides (such as MelA) and present or cross-present antigens to CD4 or CD8 T-cells, respectively." (PMID 37190135, 2023). "Immunohistochemical staining of the tumor cells showed positivity for CD2, CD3, CD4, CD5, CD25 and CD45 and partial loss of CD7." (PMID 36975591, 2023). "For example, lncRNA NNT-AS1 impairs TGF-β signaling and reduces CD4+ T cell tumor infiltration, and thereby promotes HCC progression and metastasis." (PMID 37346034, 2023). "Functionally, these cytotoxic CD4+ TILs are capable of direct MHC-II–dependent tumor recognition, ultimately leading to target lysis by granzymes in a manner similar to their CD8+ counterparts." (PMID 36512410, 2023). "The composition of PD-1 and TIM-3 subsets within CD4+ TILs remained relatively stable throughout the course of MC38 tumour progression, with distinct PD-1-TIM-3- (34-44%), PD-1+TIM-3- (24-26%) and PD-1+TIM-3+ (29-39%) populations apparent." (PMID 37153625, 2023). "The clonotypes that were expanded in the REP TIL samples displayed a CD4+ TCYTOTOXIC phenotype (cluster 0) from the original tumor sample for both cases." (PMID 37484198, 2023). "Consistently, Treg depletion in an experimental model of NASH-related HCC significantly limits tumour burden by increasing the hepatic abundance of INF-γ-producing CD4+ and CD8+ T-cells." (PMID 36691794, 2023). "The IFN-III signaling can target mammary epithelial cells and promote the chemokine CXCL10 production, thereby recruiting CD4+ T cells into the tumor microenvironment." (PMID 37809098, 2023). "The anti-tumor KBMA Lm stimulates effective CD4+ and CD8+ T cell responses and an increase in the number of mature DCs in colon cancer model without significantly side effects." (PMID 37868979, 2023). "The mean frequency of these anti-tumor memory T-cells in resting T-cells averaged 0.028% for CD4 T-cells and 0.11% for CD8 T-cells." (PMID 37033929, 2023). "It has been well reported that CD4+ T cells play a synergistic role with CD8+ T cells by recruiting them to the tumor site for enhancing their proliferation and effector functions." (PMID 37552209, 2023). "In this work, we demonstrate methionine-dependent regulation of CD4 T cell exhaustion in the tumor microenvironment." (PMID 37147330, 2023). "Here we show that blockade of PD-1 and CTLA-4 resulted in robust tumor suppression with functional augmentation of tumor-infiltrating CD4+/CD8+ T cells and an antitumor cytokine milieu." (PMID 37449205, 2023). "Most cell therapy products are a combination of CD8 and CD4 T cells, and in terms of anti‐tumor killing dynamics, CD4 CAR‐T cells are slower, less prone to exhaustion, and are more persistent following antigen exposure compared to CD8 T cells." (PMID 38023726, 2023). "The DCs present the tumor antigens to CD4+ helper T cells and CD8+ cytotoxic T lymphocytes (CTLs), leading to their activation." (PMID 37681891, 2023). "Clinical studies investigating the effect of LAMP-1 mRNA-loaded DC vaccines in glioblastoma have observed exceptional tumor-specific CD4+ and CD8+ T cell response and extended overall patient survival (Phase I, NCT00626483, NCT00639639; Phase II, NCT02366728)." (PMID 37681880, 2023). "Our results suggest that CD4 + Th1 cells are involved in the anti-tumor response generated by the TOP2A vaccine." (PMID 37880313, 2023). "Although CD4+ helper T cells inhibit tumor growth in an indirect fashion by promoting and enhancing the effector functions and memory functions of cytotoxic T lymphocytes, cytotoxic CD4+ T cells can directly kill tumor cells in antitumor immunity." (PMID 37162299, 2023). "The combination treatment of Abrine and anti-PD-1 antibody has a synergistic effect on suppressing the tumor growth through up-regulating CD4+ or CD8+ T cells, down-regulating the Foxp3+ Treg cells, and inhibiting the expression of IDO1, CD47, and PD-L1." (PMID 37334368, 2023).
tumor (continued). "Tregs are CD4+T cells that suppress the antitumor activities of CTLs, thereby promoting tumor progression." (PMID 37908722, 2023). "In the tumor microenvironment, immunosuppressive factors secreted by tumor cells lead to increased frequency of CD4+Foxp3+ Tregs and MDSCs, which creates an immunosuppressive environment that reduces CD8 activity." (PMID 38035069, 2023). "This allowed us to inject the same number of CD8+ T cells as above, but now in combination with potentially tumor-induced immunosuppressive cells such as CD4+ Tregs and MDSCs existing in the spleen." (PMID 37700795, 2023). "Except for IGLC4, IGLC5, and IGLC7, 4 IGLC (IGLC1, IGLC2, IGLC3, and IGLC6) expressions were positively correlated with infiltration scores of 6 tumor-infiltrating immune cells (B cell, T cell CD4, T cell CD8, neutrophil, macrophage, and DC)." (PMID 37784026, 2023). "In Patients 1 and 3, in which both tumor neoantigen-specific CD4+ and CD8+ T cells were activated and proliferated after the hybrid neoantigen-pulsed DC vaccine, a remarkable antitumor effect was sustained." (PMID 37881436, 2023). "A deeper understanding of the specific roles played by CD4 + T Conv cells in hypoxia-driven tumor progression is therefore necessary." (PMID 36627705, 2023). "Most importantly, the orthotopic tumors induced an anti-tumor response, including CD4+ and CD8+ T cells, as well as NK-cell infiltration." (PMID 38111571, 2023). "Compared with S100 monotherapy, CD4+ T cells showed little effect on the anti-tumor immunity of S100; whereas with the addition of αTim-3, CD4+ T cells contributed to the anti-tumor response." (PMID 37771774, 2023). "The infiltration levels of resting CD4 memory T cells, activated CD4 memory T cells, monocytes, M2 macrophages, resting mast cells, and neutrophils were significantly higher in tumor tissues than in normal tissues." (PMID 36308553, 2023). "Further, we evaluated the correlation between TRPM2 and tumor-infiltrating immune cells including B cell, CD4+ T cell, CD8+ T cell, macrophage, neutrophil, and myeloid dendritic cells." (PMID 37608401, 2023). "GK-1 decreased PD-1 overexpression only in tumor CD4+ (28 daft) and CD8+ (21, 28 daft) T cells (respectively)." (PMID 37736849, 2023). "CD4 T cells derived from regressing tumors exhibited tumor-specific HLA-II-restricted tumor cell killing ex vivo." (PMID 37185301, 2023). "Dendritic cells (DCs) are professional APCs and can cross-present tumor antigens to naïve CD4+ T cells and CD8+ T cells within secondary lymphoid organs, mainly in the draining lymph nodes." (PMID 39872303, 2023). "This is because BRAF inhibitors are supposed to modulate the tumor immune microenvironment by increasing interferon-gamma production on intratumoral CD4+ T lymphocytes and increasing CD8+ TILs." (PMID 37569757, 2023). "Tumor cells promote PD-1/PD-L1 immune checkpoint triggering through upregulation of lncSNHGs, which can lead to apoptosis of CD4+ T cells, CD8+ T cells, and reduced infiltration." (PMID 37006268, 2023). "Our previous work in this model system has shown that anti-tumor memory CD4 and CD8 T-cells accumulate in the peritoneum following IP tumor challenge in tumor-cured mice." (PMID 37033929, 2023). "Baseline CD4+ T cell counts, CVD, tumor, and initial ART drug are strongly associated with poor immune recovery." (PMID 37928477, 2023). "The median densities of CD8, CD4, Treg, TAMs, and MDSCs were 2.6e7, 3.2e7, 5.4e6, 3.7e6, and 4.2e4 cells/mL in the tumor, which were in agreement with multiple digital pathology analyses." (PMID 37291190, 2023). "In HCmel12 CRISPR-ctrl tumours, CD4+ T cells arrested both in the stromal and the tumoural compartment within the invasive margin, whereas CD8+ T cells remained highly motile in the stroma and only arrested in the tumoural compartment." (PMID 37316667, 2023).